IL6 (interleukin 6)
Diseases named in the same sentence as IL6 in open-access papers (continued):
Sharing a sentence is not in itself a finding about the gene and the disease.
liver cancer (continued). "Crocin inhibits the DNA-binding activity of STAT3 in IL-6-stimulated liver cancer cells." (PMID 34639131, 2021). "Suppresses liver cancer stem cell expansion through inhibition of autocrine IL-6/STAT3 signaling." (PMID 33968749, 2021). "In recent years, an increasing number of studies have revealed that the IL-6/STAT3 signaling pathway plays a pivotal role in the development of liver cancer, and many studies have shown that inhibition of the IL-6/STAT3 signaling pathway can block the occurrence and progress of HCC." (PMID 34976809, 2021). "As a result, blocking IL-6 pathway can prolong the effects of immunotherapy for liver cancer." (PMID 33344447, 2020). "The results demonstrated that BMP2 inducing MDSCs expansion could enhance liver cancer progression via IL6 in human liver cancer as well." (PMID 32195173, 2020). "Long non-coding RNA DILC regulates liver cancer stem cells via IL-6/STAT3 axis." (PMID 33234142, 2020). "MDSCs could subsequently secrete IL6 to enhance the proliferation of liver cancer cells both in vitro and in vivo." (PMID 32195173, 2020). "Tumor cell-intrinsic Tim-3 promotes liver cancer via NF-κB/IL-6/STAT3 axis." (PMID 33234142, 2020). "In our results, we found that BMP2 signaling could enhance the expression of the Arg1 and IL6 in bone marrows, rather than iNOS, IL8, and IL10, indicating that BMP2 inducing MDSCs expansion might enhance liver cancer growth via IL6." (PMID 32195173, 2020). "BMP2 activated MDSCs to secrete IL6, further enhancing liver cancer cell proliferation." (PMID 32195173, 2020). "Leptin- and IL-6-induced signaling via their respective receptors plays a major role not only in the control of energy homeostasis, but also under pathological conditions such as liver cancer beyond dispute." (PMID 30224299, 2018). "In addition, the IL6/JAK2/STAT3 signalling pathway was demonstrated to be involved in CD90+ liver cancer stem cell function modulation in our assays." (PMID 29722127, 2018). "Consistent with earlier reports that in human cervical and liver cancer IL-17 played a role in tumor-promoting activity by enhancing IL-6 secretion, we demonstrated that elevated IL-6 in IL-17-treated OSCC cell lines has the ability to promote OSCC cells proliferation." (PMID 29515773, 2018). "In addition, the knockdown of B4GALT3 promoted fibroblast motility and led to an activation of β1-integrin-NF-κB signaling in fibroblasts, further promoting liver cancer progression by secreting interleukin (IL)-6 and IL-8." (PMID 30312173, 2018). "Functional analysis was conducted by siRNA‐mediated CD90, Gli1 and Gli3 gene knockdown, SHH treatment and application of the JAK2 inhibitor AZD1480 and IL6 neutralizing antibody in CD90+ liver cancer stem cells, followed by cell proliferation, migration, sphere formation and tumorigenicity assays." (PMID 29722127, 2018). "This study identified C-reactive protein, IL-6, C-peptide, and non-high weight adiponectin as risk factors for liver cancer." (PMID 28894136, 2017). "In addition, Estrogen and estrogen receptor signaling have been found to have a protective role in liver cancer initiation and progression via the IL-6/STAT inflammatory pathways." (PMID 29069840, 2017). "To confirm whether Raloxifene has the potential of growth-suppressive in liver cancer, we first examined the effect of Raloxifene on constitutive STAT3 phosphorylation induced by IL-6 in Hep-3B liver cancer cells." (PMID 28430601, 2017). "Therefore, we cannot investigate the role of IL-6 in the development of liver cancer using this transgenic model." (PMID 27589954, 2016). "Furthermore, IL-6 modulates the expression of several liver cancer specific genes during the inflammatory state, and autocrine IL-6 is crucial for the initiation and progression of HCC9." (PMID 27080032, 2016). "Overall, our data suggests that upregulation of TNF-α, P65 and IL-6 may reduce the PXR levels thereby influencing its cellular functions in hepatic cancer tissues." (PMID 27760163, 2016).
liver cancer (continued). "Altogether, from our own data we cannot exclude the possibility that besides IL-6, other factors may also contribute to gender disparity in liver cancer." (PMID 25741592, 2015). "IL-6 levels in patients with liver cancer are markedly higher than those in normal individuals." (PMID 24348829, 2014). "The present study shows that the knockdown of AEG-1 may inhibit cell proliferation and promote apoptosis in the liver cancer HepG2 cell line, and the molecular mechanism may involve the suppression of IL-6 secretion and the inhibition of Stat3 activation." (PMID 24348829, 2014). "Overall, the findings suggest that aberrant AEG-1 expression promotes the growth of HepG2 liver cancer cells, contributing to the progression of liver cancer, which may partly be mediated by IL-6 signaling." (PMID 24348829, 2014). "For instance, IL-6/JAK/STAT3 signaling enhances bladder cancer cell growth and is linked to targeted kinase inhibitor resistance, while TLR4 activation facilitates inflammation-associated carcinogenesis and liver cancer metastasis through protein tyrosine kinase 2 (PTK2) induction." (PMID 41573719, 2025). "Reducing IL-6 expression may inhibit liver cancer progression and increase treatment sensitivity." (PMID 39200381, 2024). "Moreover, inhibition of IL-6/gp130 signaling can benefit patients with liver cancer." (PMID 37391912, 2023). "Notably, elevated serum IL-6 levels have been detected in patients with primary liver cancer." (PMID 37892997, 2023). "Therefore, we speculated that RasGRP1 may inhibit the development of liver cancer by inhibiting EGFR-SOS1-Ras-ERK signalling pathway activation to suppress the tumour-promoting effect of IL-6 during the acute inflammatory response." (PMID 36385095, 2022). "Next, we wondered whether autocrine IL-6 could stimulate cell proliferation of liver cancer." (PMID 34657635, 2021). "Furthermore, BMP2 signaling-activated MDSCs could secrete IL6 to enhance cell proliferation of liver cancer cells in vitro and facilitate liver cancer growth in vivo." (PMID 32195173, 2020). "We also observed that IL6 could promote cell proliferation of liver cancer cells H22 and Hepa1-6 in vitro, and the IL6 neutralized antibody could block the enhancement of cell proliferation and tumor sphere formation of Hepa1-6 induced by MDSC-secreted cytokines." (PMID 32195173, 2020). "A previous study showed that lncRNA down-regulated in liver cancer stem cells (lncRNA DILC) regulated behaviors of liver cancer stem cells via IL-6/STAT3 axis, so we supposed that lncRNA DILC might be associated with the progression of neuropathic pain through regulating STAT3 activation." (PMID 32510145, 2020). "Therefore, from these results, we cannot exclude the possibility that besides IL-6 other factors may also contribute to gender disparity in liver cancer." (PMID 25741592, 2015). "This study aims to develop a prediction model for invasive metastasis of primary liver cancer based on serum extracellular matrix metalloproteinase-inducing factor (CD147) and interleukin-6 (IL-6)." (PMID 40919145, 2025). "Wogonin supplementation is believed to reduce cytokines such as IL‐6 and TNF‐ and reduce PPAR‐mediated phosphorylation that subsequently decreases the viability of RAW264.7 cells in liver cancer conditions." (PMID 41164269, 2025). "Binary Logistics regression analysis indicated that ECV, CRP, IL-6, and NEU were factors influencing the efficacy of ICIs in liver cancer patients (P < 0.05)." (PMID 41199834, 2025). "IL‐1β from liver cancer cells activates EGFR signaling in Kupffer cells via ADAM17 (also known as TACE), leading to IL‐6 production through JNK, p38, and IKK signaling." (PMID 40859900, 2025). "CAFs also promote the stemness of CD24+ liver cancer cells by secreting HGF and IL-6, which can activate STAT3 phosphorylation at the Tyr705 site, to drive self-renewal, chemotherapy resistance, and distant metastasis." (PMID 40755769, 2025).
liver cancer (continued). "Liver cancer biomarkers were assessed in all groups through COX-2, MMP-3, HSP90, VEGF (vascular endothelial growth factor), and Interleukin-6 (IL-6)." (PMID 39281276, 2024). "Estrogen can inhibit IL-6 secretion by KCs and reduce IL-6 concentration in the circulation of DEN-treated female mice, preventing the formation of liver cancer." (PMID 38605023, 2024). "By secreting vital cytokines and chemokines like HGF, TGF-β, PDGF, IL-6, and Wnt ligands that can directly affect the tumor cells, HSC activation can also directly impact the formation of liver cancer." (PMID 37790613, 2023). "Abnormal levels of cytokines such as HGF, VEGF, TNF-α, and IL-6 are often detected in the serum of HCC patients and are closely related to liver cancer prognosis." (PMID 37663266, 2023). "In particular, we investigated the impact of IL-1β, IL-6, TNF-α, and TGF-β on PLIN5 expression in different human liver cancer cell lines." (PMID 37108378, 2023). "Using the 20 HCC tissues that were collected from HBV- and HCV-negative male HCC patients by the Taiwan Liver Cancer Network, the mRNA expression of TLR4, IL6 and CCL2 was determined using the quantitative polymerase chain reaction (qPCR)." (PMID 35955552, 2022). "At present, most scholars mainly focus on the balance of various inflammatory factors and Th1/Th2 as the prognostic indicators of liver cancer after TACE, especially IL-6, it is considered to be an important survival predictive factor." (PMID 35965593, 2022). "IL-6, phosphorylated JAK2 and phosphorylated STAT3 protein levels were significantly increased in liver cancer cells." (PMID 36591515, 2022). "For example, in pancreatic and liver cancers under irradiation, fibroblasts increase the secretion of various humoral factors including cytokines such as bFGF, TNF-a, VEGF, IL-6, EGF, MMP-2, and MMP-9." (PMID 35089951, 2022). "The complex interaction of different proinflammatory factors (such as interleukin-6 or TNF-α) with anti-inflammatory cytokines (TGF-α and TGF-β) and their signaling pathways is involved in the occurrence and development of liver cancer." (PMID 35027925, 2022). "The treatment of liver cancer cells with JAK2 inhibitor and IL-6 neutralizing antibody enhanced the adriamycin-induced aging of cells, and also significantly inhibited the proliferation rate of the cells." (PMID 36591515, 2022). "LncRNA down-regulated in liver cancer stem cells (lnc-DILC) has an inhibitory role in liver cancer stem cells’ self-renewal and suppresses its expansion by down-regulation of IL-6 transcription and STAT3 activation." (PMID 36207500, 2022). "Especially in the stages from liver cancer progenitor HcPCs to established HCC, autocrined IL-6 of HcPCs drives their progression to fully established HCC." (PMID 36333807, 2022). "The occurrence and development of liver cancer is regulated by the immune system, and a lot of important immune molecules, CD44, IL-6, CLCX8." (PMID 35602902, 2022). "Despite what is known about the role of IL-6 in stimulating hepatocytes to grow after partial hepatectomy, the actual function of the IL-6/STAT3 pathway in tumorigenesis and liver cancer is elusive." (PMID 35892823, 2022). "In this NMA study, compared with ST alone, combined TCM can significantly reduce the expression of VEGF, ICAM-1, IL-6, and TGF-β levels, thus improving the immunity of liver cancer patients." (PMID 36118529, 2022). "The levels of IL-6, phosphorylated JAK2 and phosphorylated STAT3 were significantly increased in liver cancer cells." (PMID 36591515, 2022). "In liver cancer cells, IL-37 inhibited IL-6 expression by hindering the STAT3 pathway, thereby inhibiting the inflammatory response of IL-6." (PMID 35741608, 2022). "The distribution of IL-6–174 G/C genotypes represents that GC is the most prevalent genotype amongst male and female HCV-induced hepatic cancer patients (male = 27.46%, female = 32.20%)." (PMID 36215278, 2022).
liver cancer (continued). "Multiple studies have shown a role for IL-6 in inflammation leading to liver cancer, and even gender disparities in HCC have been explained by the interrelation between estrogen and IL-6." (PMID 33918270, 2021). "In this study, we identified a novel mechanism in which TDO2, through Trp/Kyn metabolism, activated AhR/IL-6/STAT3/NF-kB signaling and promoted liver cancer progression." (PMID 34657635, 2021). "Hepcidin expression is positively correlated with BMP6/interleukin -6 (IL6) cytokines and cytotoxic immune infiltration in liver cancer tissues." (PMID 34858857, 2021). "Therefore, it is of paramount importance to delineate the predominant cause of liver cancer in distinct populations, and to investigate how the underlying cause can affect the expression and activity of CYP2D6, and the release of proinflammatory cytokines, mainly IL6." (PMID 34597305, 2021). "Mechanistically, IL-6/JAK1 pathway promotes PD-L1 phosphorylation, which seems to be the main driving factor of cancer immune escape in mouse model of liver cancer." (PMID 33344447, 2020). "MyD88 signaling induces translocation of NF-κB to the nucleus and the transcription of cytokines such as IL-6 and TNF-α that are essential for the initiation of DEN-induced liver cancer." (PMID 31049358, 2019). "Here, we aimed at evaluating circulating levels of IL-6, IL-8, and CCL22 as serum markers for patients undergoing TACE for primary and secondary liver cancer." (PMID 29899223, 2018). "The stem cell properties of CD90+ liver cancer cells are regulated by the downstream SHH/Gli and IL6/JAK2/STAT3 signalling pathways." (PMID 29722127, 2018). "In contrast, knockdown of Gli1 and Gli3 significantly down‐regulated IL‐6, phosphorylated JAK2, phosphorylated STAT3protein abundances in CD90+ 97L liver cancer cells." (PMID 29722127, 2018). "One of the most important downstream target genes of IL-6 is STAT3, which is constitutively activated in various types of cancer, including liver cancer." (PMID 28430601, 2017). "As IL-6/GP130/STAT3 signaling is essential for cell viability and colony formation in liver cancer cells, we examined cell viability by MTT assay." (PMID 28430601, 2017). "In this direction, we examined the expression of inflammatory proteins IL6, STAT3, TNF-α and NF-κB in hepatic cancer tissues." (PMID 27760163, 2016). "Therefore, we focused on the role of IL6 in tumor progression and measured the serum levels of IL6 in patients with HCC across stages A, B, and C of the Barcelona Clinic Liver Cancer (BCLC) classification." (PMID 39744421, 2025). "Cytokines such as TNF-α, IL-6, and IL-1β can increase CD55 expression in liver cancer cells." (PMID 40596619, 2025). "Therefore, our findings suggested that reduced SOCS3 expression coupled with enhanced STAT3 phosphorylation activated the IL6/JAK/STAT signaling pathway, resulting in an elevated incidence of primary liver cancer in FXR−/− mice." (PMID 39940889, 2025). "Besides, accumulating evidences have demonstrated that paeonol and forsythoside A, the effective components in JJJG, can act on the key pathological mechanism of (IL-6, TNF-α, IL-1β)/JAK2/STAT3/VEGF in the treatment of liver cancer and acute lung injury." (PMID 39494342, 2024). "Elevated IL-6 levels contribute to the development of HCC and may be a key factor in the dimorphism of liver cancer." (PMID 38605023, 2024). "The result shows that the injection of HDW could significantly reduce the liver lesion area and the serum levels of IL-6, IL-17, TNF-α, and IL-1β in the orthotopic liver cancer mouse model, and these results were dose-dependent to some extent." (PMID 36647454, 2023). "As we found that IL-6 induces STAT1 transcriptional activity upon STAT3 depletion, we next sought to analyze the expression of STAT1 and STAT3 regarding infiltrating immune cells in human liver cancer tissues." (PMID 35267462, 2022).
liver cancer (continued). "In addition, lnc-DILC modulates the crosstalk between TNF-α/ NF-κB signalling and IL-6/STAT3, resulting in a decreased hepatic inflammation and liver cancer stem cell proliferation." (PMID 36207500, 2022). "Similarly, IL-6 enhanced level in HCV also provides advantage to cancer cells by suppressing apoptosis, hence leading to hepatic cancer development." (PMID 36215278, 2022). "MiR-206 acted as a suppressor factor in liver cancer and played a suppressive role in the activation of HSCs, the crosstalk of CAFs with CCA cells reduced MiR-206 expression, which induced the conversion of NFs into CAFs and enhanced their secretion of IL6." (PMID 35971182, 2022). "There is crosstalk between transforming growth factor-β and interleukin-6 pathway, which contributes to the EMT of liver cancer cells and promotes the dedifferentiation of liver cancer cells so as to promote the progression of liver cancer." (PMID 35096588, 2021). "In hepatocytes and liver cancer cells, the expression of HBx can activate the downstream signaling proteins IRAK-1, ERKs/p38 and NF-κB of MyD88, thereby promoting the synthesis and secretion of IL-6 and promoting the progress of HBV-related HCC." (PMID 35096574, 2021). "Meanwhile, inhibitors of the IL-6/STAT3 signaling pathway should be promoted, and the efficacy and safety of these targeted inhibitors should be evaluated, it is need to formulate the standardization of clinical individualization treatment for liver cancer." (PMID 34976809, 2021). "Its negative association with IL6 proclaims an intricate relationship between CYP2D6 and inflammation in the ethnic differences seen in AS and CA liver cancer patients." (PMID 34597305, 2021). "Overall, consideration of the IL-6/STAT3 signaling pathway, and its role in the carcinogenesis and progression of HCC will contribute to the development of potential drugs for targeting treatment of liver cancer." (PMID 34976809, 2021). "Moreover, the proliferation rates of liver cancer cells were also greatly suppressed by treatment with the JAK2 inhibitor and IL6 neutralizing antibody." (PMID 29722127, 2018). "Raloxifene is a suitable agent for targeting liver cancer and possibly certain type of cancer cells with constitutively activated STAT3 induced by IL-6, due to its ability to inhibit IL-6/GP130 binding as well as their potent growth suppressive activity both in vitro and in vivo." (PMID 28430601, 2017). "As the up-stream of STAT3, inhibition the binding of IL-6 and GP130 may also exhibit potent growth-suppressive activity in liver cancer cells." (PMID 28430601, 2017). "So, in this study, we further investigated whether Raloxifene has the ability to inhibit IL-6/GP130/ STAT3 signaling and suppress tumor growth in liver cancer cells." (PMID 28430601, 2017). "Our results suggest that Raloxifene is a potent IL-6/GP130 inhibitor and may be a chemoprevention agent for liver cancer by targeting persistent STAT3 signaling." (PMID 28430601, 2017). "The expression of IL-6 was observed to be 2.4 fold upregulated at the protein level and that for Stat3 about 3.5 fold upregulated at transcript level in DEN-induced hepatic cancer as compared to control mice." (PMID 27760163, 2016). "Additionally, IL-6 induced STAT3 phosphorylation in the nucleus, which was blocked by LY5 pre-treatment in Hep3B liver cancer cells." (PMID 26883202, 2016). "Previously, in EPIC, we reported on the positive association between IL-6 and HCC independent of adiposity and metabolic biomarkers, which suggests a role for innate immunity in liver cancer pathogenesis." (PMID 26561631, 2015). "For instance, high BMI boosts Interleukin-6 and tumor necrosis factor production, triggering hepatic inflammation and activating the oncogenic transcription factor STAT3 (signal transducer and activator of transcription 3), thereby driving liver cancer progression." (PMID 40717954, 2025).